CTLA4 (cytotoxic T-lymphocyte associated protein 4)
Diseases named in the same sentence as CTLA4 in open-access papers (continued):
Sharing a sentence is not in itself a finding about the gene and the disease.
melanoma (continued). "These genes included SKP2, TOP2A, SOX4, MAP2 and CTLA4, all of which have been associated with patient outcome in melanoma." (PMID 29193607, 2018). "High somatic copy number alterations in melanoma patients have recently been linked with less effective response to immune checkpoint blockade anti–CTLA-4 (cytotoxic T lymphocyte–associated protein 4) therapy." (PMID 29760781, 2018). "Anti-cytotoxic T lymphocyte-associated antigen 4 (CTLA-4) and anti-programmed cell death protein-1 (PD-1) have especially been beneficial to ailments, such as melanoma." (PMID 29473044, 2018). "This lack of sensitivity to IFN-γ results from loss of heterozygosity mutations in JAK 1 and 2, and similar to mouse models, these mutations were noted in melanoma patients that were resistant to anti-CTLA4 treatment." (PMID 29502288, 2018). "Monoclonal antibodies against T-cell checkpoint proteins, such as CTLA-4, PD-1, and PD-L1, have now been approved for melanoma treatment and are associated with robust durable responses, but only in a subset of tumors." (PMID 29946530, 2018). "For example, low absolute monocyte counts and high absolute eosinophil counts at baseline were associated with a favorable outcome in melanoma patients (n = 209) treated with anti-CTLA-4." (PMID 29968076, 2018). "In recent years, monoclonal antibodies blocking the inhibitory programmed cell death 1 pathway (PD-1/PD-L1) and the cytotoxic T lymphocyte associated protein 4 (CTLA-4) have significantly impacted the treatment of advanced melanoma." (PMID 29988983, 2018). "Immune checkpoint inhibitors, including anti-PD-1, anti-PD-L1, and anti-CTLA-4 (cytotoxic T-lymphocyte-associated protein 4) antibodies, have become the standard therapy for malignant melanoma." (PMID 30487384, 2018). "Combination immunotherapy with nivolumab and ipilimumab, another immune checkpoint inhibitor blocking cytotoxic T-lymphocyte-associated protein 4 (CTLA-4), has been shown to be superior to monotherapies in treating some solid tumors including melanoma." (PMID 29685160, 2018). "Interferon-γ pathway loss has been associated with resistance to CTLA-4 blockade in melanoma making it a potential biomarker of immune evasion and poor response to therapy." (PMID 30568917, 2018). "The combination of nivolumab and ipilimumab [anti-PD-1 and anti-cytotoxic T-lymphocyte-associated protein 4 (CTLA-4)] showed an intracranial response rate of 55% in patients with melanoma brain metastases." (PMID 30319977, 2018). "It demonstrated that increasing mutational load was associated with higher response rate to anti–CTLA-4 in melanoma and anti–PD-1 in lung cancer, indicating that the recognition of mutated neoantigen plays a crucial part in the antitumor immune response." (PMID 28418918, 2017). "Immune checkpoint blockade via the inhibition of cytotoxic T-lymphocyte associated protein 4 (CTLA-4) and programmed death protein 1 (PD-1) receptors has shown recent success in the treatment of melanoma, non-small cell lung cancer, and renal cell carcinoma." (PMID 29379468, 2017). "A separate study examined the peripheral TCR repertoire in anti-cytotoxic T-lymphocyte-associated protein 4 (CTLA-4)–treated patients with prostate cancer or melanoma and found that clonotype stability was associated with response." (PMID 28552987, 2017). "In particular, abscopal responses were documented in several melanoma patients when RT was associated with α-CTLA4 drugs as ipilimumab, and/or α-PD-1/PD-L1 antibodies as nivolumab and pembrolizumab." (PMID 29163540, 2017). "No other potentially pathogenic variants were identified in other melanoma or gastric cancer predisposing genes or in CTLA4 gene." (PMID 28720148, 2017). "Ipilimumab, a fully human IgG1 monoclonal antibody directed against cytotoxic T-lymphocyte associated antigen 4 (CTLA-4), is approved for the treatment of malignant melanoma." (PMID 28134806, 2017).
melanoma (continued). "Both anti-CTLA-4 and anti-PD-1/PD-L1 mAbs are revolutionizing the clinical approach to melanoma patients regardless the mutational status." (PMID 29290886, 2017). "In melanoma patients specific gut microbiota patterns have been recently linked to improved response rate to ipilimumab (CTLA-4 inhibitor) but also to an increased occurrence of ipilimumab-induced colitis." (PMID 28919861, 2017). "CTLA-4 or PD-1/PD-L1 blockade is associated with increased survival in melanoma, renal cell cancer, non-small cell lung cancer, bladder cancer, and Hodgkins lymphoma." (PMID 27714433, 2017). "IDO has been implicated in promoting T cell resistance to anti-CTLA-4 Ab blockade in murine melanoma models." (PMID 28239469, 2017). "The present study assessed the potential role of defined CTLA-4 gene variants in predicting clinical outcome in patients with advanced melanoma treated with IPI." (PMID 28446908, 2017). "Melanoma somehow appears to be capable of rendering T-cells anergic in vivo, either through CTLA-4, PD-1, mutational burden, or other molecular means." (PMID 29179523, 2017). "More recently, the clinical success of checkpoint inhibitors in melanoma patients has revealed an additional predictive role of the mutational load in patients treated with either anti-PD-1 or anti-CTLA-4 antibodies." (PMID 29312332, 2017). "Currently, the treatment of advanced malignant melanoma made use of immuno-therapy with PD-1 and CTLA-4 inhibitors and, for melanomas harboring BRAF mutation, also, of target therapy with BRAF and MEK inhibitors." (PMID 29100280, 2017). "The efficacy of this approach was first proven in patients with advanced melanoma based on the improved overall survival (OS) of patients treated with the anti-cytotoxic T lymphocyte associated protein 4 (CTLA-4) directed monoclonal antibody ipilimumab." (PMID 28239469, 2017). "Ipilimumab is a human monoclonal antibody that functions as a cytotoxic T-lymphocyte-associated antigen 4 (CTLA-4) inhibitor that is used to treat malignant melanoma." (PMID 28533998, 2017). "Silencing CTLA-4 or GITR on DC enhanced the induction of antitumor CTLs in response to DC transfected with mRNAs encoding either melanoma or breast cancer antigens." (PMID 27827885, 2016). "In that regard, one study in melanoma showed that patients harboring tumors with >100 mutations were more prone to benefit from anti-CTLA4 treatment, suggesting a threshold for ICB molecule efficacy." (PMID 28003994, 2016). "Antibodies against programmed death 1 (PD-1) receptor and cytotoxic T-lymphocyte-associated antigen 4 (CTLA-4) have transformed the systemic treatment of melanoma and many other cancers." (PMID 27660712, 2016). "Recent studies have indicated that a high tumor mutation burden increases responsiveness to CTLA-4 inhibition in melanoma, to PD-1 inhibition in non-small cell lung cancer and in mismatch repair-deficient colorectal cancers." (PMID 26943571, 2016). "In melanoma, mutational load was associated with the degree of clinical benefit to CTLA-4 blockade and pembrolizumab." (PMID 27904752, 2016). "In melanoma, the presence of TILs was shown to be functionally linked to clinical benefit obtained with checkpoint inhibitors such as antibodies blocking CTLA-4 and PD1 molecules." (PMID 27188274, 2016). "In patients with melanoma, the G allele of rs4553808 in CTLA-4 was associated with improved response to ipilimumab." (PMID 27118383, 2016). "Ipilimumab is a monoclonal antibody which targets cytotoxic T lymphocyte-associated protein 4 (CTLA-4) which is a protein receptor which can be made to switch off cytotoxic T lymphocytes (CTLs) by melanoma cells." (PMID 27841141, 2016). "PTML was strongly associated with clinical outcome to ipilimumab (anti-CTLA-4, three cohorts) and adoptive T-cell therapy (1 cohort) clinical outcome in melanoma." (PMID 27776519, 2016).
melanoma (continued). "When considering the efficacy of immune checkpoint inhibitors, promising clinical responses have been observed with anti-PD-1 and anti-CTLA-4 blockade in lung cancer and melanoma, both of which are associated with the highest cancer mutation rates." (PMID 27004405, 2016). "One of the most remarkable immunomodulatory therapies of recent times is currently licensed for melanoma treatment – antibody-based inhibition of the immune checkpoints programmed cell death 1 (PD-1) and cytotoxic T lymphocyte-associated antigen 4 (CTLA-4)." (PMID 27301245, 2016). "The first of these checkpoint inhibitors to reach the clinic was an anti-cytotoxic T-lymphocyte-associated protein 4 (CTLA-4) antibody, ipilimumab, which first demonstrated effectiveness in the treatment of melanoma in 2008." (PMID 27068940, 2016). "For instance, according to two independent groups, the mutational frequency in melanoma tumors was correlated with clinical responses to anti-CTLA-4 therapy." (PMID 27151159, 2016). "As evidence that anti-CTLA-4 antibody blockade effectively induces the activation of self-reactive T cells in melanoma patients, studies have associated the induction of autoimmune side-effects with clinical response." (PMID 25992290, 2015). "Genetic silencing of PD-L1 caused the melanomas to again become sensitive to anti-CTLA-4 therapy and radiation." (PMID 26709361, 2015). "We did not observe a significant association between FM and HSL-CGP-mutational loads and DCB in melanoma patients treated with CTLA-4 blockade." (PMID 26439694, 2015). "In B16 murine melanoma models, MV encoding anti-CTLA-4 and anti-PD-1 enhanced therapy, delaying tumour progression and increasing survival." (PMID 26633468, 2015). "This analysis was carried out to assess if BRAFV600 and NRAS mutation status affects the clinical outcome of anti-CTLA-4-treated melanoma patients." (PMID 26426340, 2015). "The other successful approach of enhancing antitumor immunity against melanoma included the administration of a mAb (ipilimumab) which blocks cytotoxic T-lymphocyte-associated antigen 4 (CTLA-4) to potentiate an antitumor T-cell response." (PMID 26648938, 2015). "Checkpoint blockade with antibodies to activate immune responses and perhaps to counteract melanoma-associated immunomodulatory mechanisms led to the first clinical breakthrough in the form of an anti-CTLA4 monoclonal antibody." (PMID 24969320, 2014). "We previously genotyped 286 melanoma patients and 288 healthy (unrelated) individuals for six CTLA-4 polymorphisms (SNP)." (PMID 24475110, 2014). "Clinically, a combination of local irradiation and anti-CTLA-4 antibody therapy caused regression of metastatic tumors at a distance from the irradiated site (abscopal effect) in a melanoma patient." (PMID 24686897, 2014). "Cytotoxic T-lymphocyte-associated antigen 4 (CTLA4) antibodies were the first immunotherapeutic agents for melanoma with remarkable clinical response." (PMID 25361008, 2014). "CTLA4 polymorphism has been reported in association with degree of responsiveness in melanoma patient treated by CTL-4 blockade." (PMID 22911710, 2012). "We tested the association of variants in FOXP3 microsatellites, CTLA4 SNPs and HLA genotype in 284 melanoma patients and their association with prognosis and survival of melanoma patients who received IFNa adjuvant therapy." (PMID 22911710, 2012). "Recently, the antibody directed against an immune response inhibitory molecule, called cytotoxic T lymphocyte associated protein 4 (CTLA4), known as Yervoy®, has shown promising clinical efficacy in melanoma patients." (PMID 24955288, 2012). "The frequency patterns of CTLA-4 alleles were first evaluated in the healthy control and melanoma populations." (PMID 21044351, 2010). "In malignant melanoma patients, two antibodies are being studied with this indirect approach, both targeting “Anti-cytotoxic T lymphocyte-associated antigen 4” (CTLA-4)." (PMID 20224761, 2010).
melanoma (continued). "This study analyzed the potential influences of the CTLA-4 genotype upon the outcome of IFN adjuvant therapy, on the basis of prior suggestions of the role of certain polymorphisms of the CTLA-4 gene and other immunotherapies for patients with melanoma." (PMID 21044351, 2010). "These provocative findings stimulated detailed investigation of the polymorphisms of CTLA-4 in larger numbers of patients treated in a subsequent study of 152 stage IV melanoma patients at the NIH." (PMID 21044351, 2010). "The purpose of this study is to examine, at a population level, the extent to which use of anti-PD-1/CTLA-4 combination immunotherapy is associated with an increased incidence of adverse neurologic events in melanoma patients in comparison to monotherapy PD-1 inhibitor regimens." (PMID 40351833, 2025). "Further IFN-γ enhances CTLA-4 expression on melanoma cells which causes immune evasion." (PMID 40236693, 2025). "This study provides evidence that melanoma patients receiving PD-1 inhibitor therapy in combination with CTLA-4 inhibitor therapy are at greater risk of experiencing immune-related neurologic adverse events than patients on anti-PD-1 monotherapy treatment regimens." (PMID 40351833, 2025). "ICIs targeting programmed cell death protein 1/programmed cell death protein 1 ligand (PD-1/PD-L1) and cytotoxic T-lymphocyte-associated protein 4 (CTLA-4) in T cells have revolutionized cancer treatment and have shown impressive clinical results in solid tumours such as melanoma." (PMID 40650066, 2025). "Early studies reported that greater baseline gut microbiota richness and diversity were associated with improved responses to ICIs, including anti-CTLA-4 and anti-PD-1 therapies in melanoma and epithelial cancers, while antibiotic use was linked to diminished clinical benefit." (PMID 41472726, 2025). "Notably, melanoma patients with low-risk mRNAsi were found to respond better to anti-CTLA-4 therapy." (PMID 41233805, 2025). "Melanoma is classified as an immunologically “hot” tumor, characterized by high levels of tumor-infiltrating lymphocytes (TILs), elevated expression of immune checkpoint molecules (e.g., PD-1, CTLA-4), and a high tumor mutational burden (TMB)." (PMID 40867277, 2025). "This study examines whether combination anti-PD-1/CTLA-4 immunotherapy for melanoma is associated with increased incidence of neurologic irAEs (n-irAEs) compared to anti-PD-1 monotherapy." (PMID 40351833, 2025). "According to previous studies, the effect of TLS on immunotherapy such as PD-(L) 1 or PD-(L) 1 combined with cytotoxic T lymphocyte-associated protein 4 (CTLA-4) blockade is mostly positive, which has been demonstrated in multiple immunotherapy cohorts such as melanoma and bladder cancer." (PMID 40612858, 2025). "In melanoma, PD-1 inhibitors (nivolumab, pembrolizumab) were mainly linked to thyroid dysfunction (40–45%) and autoimmune diabetes (10–15%), while anti-CTLA-4 agents (ipilimumab, tremelimumab) were predominantly associated with hypophysitis (up to 60%) and adrenal insufficiency (6–11%)." (PMID 41301042, 2025). "Also, for the clinically more relevant combination of anti-PD-1 and anti-CTLA-4, we found strongly reduced antitumor activity in mice bearing melanoma with genetic deficiency for MLKL." (PMID 40345706, 2025). "Although the role of CTLA‐4 upregulation in tumour cells remains unclear, the level of CTLA‐4 expression in melanoma cells has been associated with clinical response to the CTLA‐4 inhibitor ipilimumab, supporting its possible role as a predictive biomarker." (PMID 39789732, 2025). "It is also well established that treatment with anti-PD-1/anti-CTLA-4 combination in the 1L setting in the BRAF-mutated melanoma patients results in better outcomes when compared to the use of targeted therapy, as demonstrated in the SECOMBIT and DREAMseq trials." (PMID 40027067, 2025).
melanoma (continued). "For instance, tumor models responsive to CTLA-4 blockade commonly have a higher CD4+ T cell population, and the presence of pre-existing CD4+ T cells in the bloodstream has been shown to be associated with improved clinical outcomes in melanoma patients undergoing anti-CTLA-4 treatment." (PMID 40857744, 2025). "IFN-γ in the tumor microenvironment might affect the response to a combination of anti-PD-1 and anti-CTLA-4 agents by inducing apoptosis in tumor-reactive T-cells in melanomas with a low mutational burden." (PMID 40108693, 2025). "Furthermore, reduced expression of UPR target genes such as XBP1s, ATF4, and BiP was observed in the B2905 mouse melanoma model upon anti-cytotoxic T lymphocyte-associated antigen 4 (CTLA-4) ICI." (PMID 41372991, 2025). "Immune checkpoint inhibitors, especially those targeting cytotoxic T-lymphocyte associated protein 4 (CTLA-4) and programmed cell death protein 1 (PD-1), proved effective in treating various solid tumors, such as melanoma, renal cell carcinoma and non-small cell lung cancer." (PMID 40145087, 2025). "Transcriptomic analysis from the melanoma patients reveals that responsiveness to the pretreatment with anti-CTLA-4 showed a positive correlation with increased tumor mutational burden (TMB) and increased expression of neoantigen and cytolytic markers in the immune microenvironment." (PMID 39195270, 2024). "However, a recent study has shown that high levels of IL-17A in the baseline peripheral blood of patients with melanoma are associated with better clinical responses to dual ICB therapy (anti-PD-1 + anti-CTLA-4)." (PMID 38675738, 2024). "Melanoma escapes immune surveillance by manipulating immune checkpoints, such as programmed cell death protein 1 (PD-1), programmed death-ligand 1 (PD-L1), and cytotoxic T-lymphocyte-associated protein-4 (CTLA4)." (PMID 38893071, 2024). "The use of immune checkpoint blockade (ICB) therapies, including antibodies targeting programmed cell death 1 (PD-1) and cytotoxic T-Lymphocyte-associated Protein 4 (CTLA-4), alone or in combination, has marked a significant advancement in the treatment of malignant tumors like melanoma." (PMID 38893208, 2024). "Current immunotherapies for advanced stage melanomas involve antagonization of cytotoxic T-lymphocyte-associated protein-4 (CTLA-4, ipilimumab) and programmed cell death protein-1 (PD-1, nivolumab and pembrolizumab), but in 45-70% of cases these therapies encounter primary resistance." (PMID 38426087, 2024). "The melanoma treatment-associated sensitivity analysis conducted on the low- and high-risk subgroups indicates that the low-risk subgroup exhibited more positive responses to CTLA4 and PD-1 therapy than the high-risk subgroup." (PMID 38900244, 2024). "Moreover, sunitinib in combination with the cytotoxic T-lymphocyte-associated protein 4 (CTLA-4) monoclonal antibody shows a synergistic antitumor effect by promoting tumor-infiltrating lymphocyte activity in melanoma and NSCLC mouse models." (PMID 39086395, 2024). "We additionally observed signals that DUX4 expression was associated with reduced survival following response to anti-CTLA-4 or anti-PD-1 in melanoma; however, those analyses relied upon two small cohorts (n = 27 or 41 patients), limiting the statistical power of our conclusions." (PMID 38829686, 2024). "For instance, immune checkpoint blockade (ICB), which has revolutionized the treatment of solid tumors, currently results in a 60% response rate in those melanoma patients treated with anti-programmed cell death protein 1 (PD-1) and anti-cytotoxic T lymphocyte-associated protein 4 (CTLA-4)." (PMID 39236156, 2024). "Immune checkpoint inhibitors, including the antibodies that block CTLA-4 (cytotoxic T-lymphocyte-associated protein-4) and PD-1 (programmed cell death protein-1) expressed on lymphocyte membranes, aim to enhance T-cell infiltration in melanoma and stimulate an immune response against the tumor." (PMID 38338893, 2024).